EGFR (epidermal growth factor receptor)
Diseases named in the same sentence as EGFR in open-access papers (continued):
Sharing a sentence is not in itself a finding about the gene and the disease.
tumor (continued). "For the first time, these findings demonstrate the tumor-promoting role of SCAMP3 in TNBC and its association with EGFR and other receptor tyrosine kinases and expose the potential to develop SCAMP3-targeted anticancer therapies to increase patient survival." (PMID 35681787, 2022). "In tumor cells, the EGFR signaling mainly activates downstream RAS/MAPK, PI3K/ Akt, PLCγ/PKC and JAK/STAT3 signaling pathways, promoting cancer cell growth and metastasis." (PMID 35637973, 2022). "In 56 FFPE tumor samples tested for changes in the EGFR gene, 26 had EGFR alterations (10 confirmed sequence alterations and 15 confirmed EGFR exon 19 deletions) while 30 were wildtype, resulting in a 100% PPA between the assays." (PMID 35595835, 2022). "EGFR has emerged as a critical target molecule for enhanced tumor specificity because of its diverse functional roles in cancer." (PMID 35455247, 2022). "As an oncolytic virus, ReoV can hijack epidermal growth factor receptor (EGFR)- and rat sarcoma virus (Ras)-activating mutations to preferentially replicate in tumor cells." (PMID 35681452, 2022). "Using targeted proteomics tools within a set of various cancer models we describe here the discovery and characterization of a composite phosphorylation signature associated with tumor addiction to four distinct oncogenes, MET, EGFR, ALK and BRAF." (PMID 36494469, 2022). "Epidermal growth factor receptor (EGFR) functions as a tumor promoter and is thus considered as a prospective therapeutic target for cancer treatment." (PMID 36387211, 2022). "Nanocarrier micelles are also able to entrap various photosensitizers and deliver them to tumors, especially when conjugated with EGFR target peptides, allowing for the targeting of EGFR-overexpressing tumor cells." (PMID 35213974, 2022). "To further explore the mechanism involved in synergistic anti-tumor effect, we examined the core protein level involved in Nrf2/HO-1 signaling and EGFR/HER2-AKT/ERK1/2 signaling pathway in both SK-BR-3 and SK-OV-3 cancer cells." (PMID 36090218, 2022). "Our study suggests that an ETTE nanoprobe can achieve dynamic monitoring of EGFR signal pathway activity during tumor therapy." (PMID 35105871, 2022). "In ESCC tumor tissues, EGFR is frequently overexpressed or often amplified, with activation of the PI3K/AKT signaling pathway due to mutations in the PI3KCA gene and loss of PTEN expression." (PMID 35216506, 2022). "The ATLANTIC study assessed the effect of durvalumab treatment in three cohorts of patients with NSCLC defined by EGFR/anaplastic lymphoma kinase status and tumor expression of PD-L1." (PMID 35838354, 2022). "The KID activity of EGFR is another possible mechanism by which EGFR inhibitors are less efficacious than expected in a range of tumours." (PMID 36497413, 2022). "Epidermal growth factor receptor (EGFR) pathway has been shown to play a crucial role in several inflammatory conditions and host immune-inflammation status is related to tumor prognosis." (PMID 36231138, 2022). "Cetuximab, on the other hand, is highly dependent on the presence of EGFR on the cell surface, and shows anti-tumor effects by inhibiting its function and blocking cell growth signaling." (PMID 35928727, 2022). "Another radiomics model reliably predicted EGFR mutations in NSCLC based on the presence of emphysema, airway abnormalities, the percentage of the ground glass component, and the type of tumor margin (AUC = 0.89)." (PMID 36359485, 2022). "In various tumor models, amivantamab efficiently downregulates the expression of EGFR and MET, and exhibited antitumor immunity with Fc-mediated effector interactions." (PMID 36432687, 2022). "In a summary, the current study demonstrated the co-expression and interaction of NK1R and EGFR in NSCLC tumor cells." (PMID 35013118, 2022).
tumor (continued). "Approximately 50%–60% of secondary resistance to primary EGFR- tyrosine kinase inhibitors (TKI) therapy is caused by acquired p.Thr790Met (T790M) mutation; however, highly fragmented, low-quantity circulating tumor DNA is an obstacle for detecting mutations." (PMID 35168603, 2022). "In line with previous preclinical studies, we found that JHU083 alone mediated beneficial anti‐tumor effects in a mutant EGFR primary lung tumor model, demonstrating ≈30% inhibition of tumor growth." (PMID 35861366, 2022). "Having established that both CT26EGFR and HT29 had intact EGFR downstream signaling pathways, we expected Cetuximab monotherapy to result in anti-tumor activity, but used it as a control arm to differentiate the immune pertinent impact of BsAb treatment." (PMID 35177811, 2022). "The understanding of the MRD state that develops after initial exposure to EGFR-TKIs such as YAP/TEAD provide an insight into how tumour cells escape from initial apoptosis." (PMID 36212398, 2022). "LUAD patients were classified into different subgroups under diverse clinical properties, including T stage, N stage, M stage, tumor stage, gender, age, smoking history, status of EGFR." (PMID 36185284, 2022). "Three models were constructed for the solid components: Model 1 (gender + tumor size), Model 2 (Model 1 + CEA), Model 3 (Model 2 + Ki‐67 + EGFR mutation + tumor differentiation)." (PMID 35289087, 2022). "Taken together, these data illustrate that blocking oncogenic EGFR signalling in tumours increased the immune cell infiltration in the TME and stimulated a proinflammatory immune response against tumours." (PMID 36010935, 2022). "The regulation of PI3K/AKT, JAK/STAT, and MAPK signaling pathways has been linked to sesamin's tumor-inhibitory activities, mediated by some typical receptor estrogen, HER2, and EGFR." (PMID 35223101, 2022). "Xue and co-workers synthesized a multitarget photosensitizer that can selectively carry out photodynamic treatments in the ER of EGFR-overexpressing tumor cells." (PMID 35213974, 2022). "Previously, it has been reported that EGFR is only expressed in a small proportion of UM tumours and immortalised cell lines." (PMID 35781872, 2022). "A retrospective study using formalin-fixed and paraffin-embedded tumor specimens suggested that the positive rate of T790M in the TKI plus bevacizumab group was significantly lower than that in the EGFR-TKI monotherapy group (51.5% vs. 35.5%, p = 0.0003)." (PMID 36230817, 2022). "When combined with ligand-EGF, EGFR can phosphorylate tyrosine residues, activate EGFR, and promote the growth and proliferation of tumor cells." (PMID 35310032, 2022). "Reduced EGFR phosphorylation, increased γH2AX foci and induced apoptosis, which resulted in suppression of tumour growth." (PMID 35889688, 2022). "The oncogenes that have successfully induced high-grade astrocytoma include Ras, Akt, EGFR, PDGFR, and often in combination with mutations in tumor suppressors such as Ink4A or Arf." (PMID 35747806, 2022). "RBM5, a tumour suppressor gene and splicing factor, improves the production of mRNAs by recognizing incorrect 3′splice sites of epidermal growth factor receptor (EGFR) pre-mRNA, thereby inhibiting the proliferation of tumour cells." (PMID 35552415, 2022). "In EGFR-mutant tumor cells cocultured with activated PBMCs, EGFR-TKI treatment increased CXCL10 in the supernatant; this activated CXCR3 in the tumor cells to induce the phosphorylation of Src and the NF-κB subunit, p65, and the expression of HIF-1α." (PMID 36612121, 2022). "Since ST6Gal-I–mediated EGFR sialylation led to increased EGFR activity, we were interested in which downstream signaling cascades regulate the increased cell mechanics and tumor-promoting cell behaviors." (PMID 35157848, 2022). "Tumor cells were opsonized by different concentrations of the anti-EGFR mAbs in a dose-dependent manner." (PMID 35035479, 2022).
tumor (continued). "To investigate this biological problem, we capitalized on a Drosophila tumor model with human relevance based on the simultaneous overactivation of the EGFR and the JAK/STAT signaling pathways." (PMID 35443185, 2022). "The role of the EGF family and the EGFR signal pathway in angiogenesis regulation and hyperplastic growth of several tissues, as well as tumor growth, is well demonstrated." (PMID 36326383, 2022). "EGFR-medicated endocytosis also enhanced toxicity against tumor cells and consequently stronger inhibition of xenograft growth in vivo." (PMID 35156493, 2022). "But the combination of cetuximab with panitumumab proved to be effective in EGFR degradation and tumour reduction in an experimental study." (PMID 36158981, 2022). "Our previous experience with water-soluble, bioavailable formulations of silibinin demonstrated a complete abrogation of tumor growth in xenograft models of EMT-driven resistance to EGFR TKIs." (PMID 36551587, 2022). "Addition of fluorescein-conjugated anti-EGFR monoclonal antibody resulted in cell lysis of EGFR-expressing tumor cells while addition of fluorescein-conjugated anti-CD38 monoclonal antibody resulted in cell lysis of CD38-expressing tumor cells." (PMID 36531912, 2022). "Amivantamab inhibits proliferation of tumor cell in NSCLC patients by effectively downregulating EGFR and MET gene levels and inducing immune antitumor activity and increasing IFNγ secretion." (PMID 36313314, 2022). "The EDVs being 400 nm rapidly fall out of these fenestrations and enter into the tumour microenvironment and since they carry the bispecific antibody on the EDV surface, the anti‐EGFR component binds to EGFR on the tumour cell surface." (PMID 34665932, 2022). "Since the discovery of activating EGFR mutation, TKIs are currently the standard of care for advanced NSCLC patients which provide strong anti-tumor activity compared to platinum-based chemotherapy." (PMID 36712972, 2022). "The nuclear localization of EGFR has been widely reported in many types of cells, especially on tumor cells." (PMID 35152831, 2022). "For example, Kim and others have shown that coupling cetuximab, an antibody against EGFR, to the liposomal surface enhances delivery of siRNA to target mice with SK-OV-3 tumor xenografts." (PMID 36499115, 2022). "Identifying the EGFR mutational status on a tumor biopsy or a liquid biopsy using tumor DNA sequencing techniques is the current approach to predict tumor response on EGFR TKI therapy." (PMID 36313723, 2022). "al. have recently demonstrated that the use of small EGFR-targeted nanobody-IRDye700DX conjugates (15 or 30 kDa) leads to higher tumour:background contrast and enhanced tumour necrosis when compared with full-size mAb-based IRDye700DX conjugate." (PMID 35057796, 2022). "EGFR inhibitors also augment DCs function and tumor antigen presentation, enabling better T cell-mediated tumor destruction." (PMID 36551637, 2022). "The three types of conjugates (i.e., QD800-RGD, QD820-anti-CEACAM1, and QD840-anti-EGFR) were simultaneously detected in vivo, especially showed great potential to be used for tumor targeting agents with specific delineation of tumor region." (PMID 34976580, 2022). "Gender, tumor size, CEA, Ki‐67, EGFR mutation (solid components only), and tumor differentiation were significantly independently associated with the containing of SMC." (PMID 35289087, 2022). "Zebrafish were inoculated with tumor cells and placed in the culture medium containing the third-generation EGFR-TKI, osimertinib." (PMID 35936715, 2022). "This study identified that CDCA enhances the anti-tumor effect of sorafenib and plays an inhibitory effect on EGFR." (PMID 35252007, 2022). "Most tested molecules promoted tumor cell death, from which two EGFR inhibitors (molecules 8 and 17), two PI3Kp110β inhibitors (molecules 19 and 20), and two dual inhibitors (molecules 25 and 27) caused more than 50% of the cell death." (PMID 35884571, 2022).
tumor (continued). "Immunofluorescence carried out on tumour cells showed that EGFR was well expressed and well activated in all tumour populations tested, as demonstrated by its specific vesicular pattern." (PMID 36380366, 2022). "An early on-treatment increase in the plasma ctDNA level of these gene alterations was correlated with the corresponding resistance mechanism to EGFR-TKIs, a finding that was confirmed in post-treatment tumor tissues." (PMID 35326664, 2022). "Genetic aberrations of 84 genes involved in the Her2/EGFR-PDGFR pathway were assessed in the tumor tissue samples obtained from the patients using SA-Bioscience assay." (PMID 35871690, 2022). "Together, these results provide evidence to support that vanadate facilitates increased NF-κB signaling favoring a proinflammatory profile in treated tumor cells by regulating IκB-ɑ through EGFR activation." (PMID 35572196, 2022). "Concomitant driver mutations included activating mutations in classic oncogenes (e.g., KRAS, NRAS, EGFR, and PIK3CA), as well as loss-of-function mutations in tumor suppressors (e.g., BRCA1/2 and PTEN)." (PMID 36369474, 2022). "Analysis of scRNA-seq data from all 28 tumors in the dataset showed that elevated CD73 expression was principally focused in two discrete clusters of AC-like and OPC-like tumor cells, which exhibited high expression of EGFR and PDGFRA, respectively." (PMID 35973991, 2022). "The EGFR/p38 signaling pathway is involved in the occurrence and development of a variety of tumors and plays an important regulatory role in tumor cell proliferation, apoptosis, invasion, and metastasis." (PMID 36200190, 2022). "It has been demonstrated that anti-EGFR mAbs had poor capacity to induce CDC of EGFR-expressing tumor cell lines in vitro, rendering a role for cetuximab-induced CDC in patients less likely." (PMID 35035479, 2022). "Physically, STAT3 interacts with NF in tumor and tumor-associated immune cells, wherein lactoglobule-EGF Factor 8 (MGF-E8)/STAT3, Sonic Hedgehog/EGFR/STAT3/Sox2 pathways, and CSC-like phenotypes were promoted by tumor-associated macrophages." (PMID 36061200, 2022). "After premetastatic niche formation, MDSCs interact with tumor cells through the IL-6 receptor (IL-6R) and epidermal growth factor receptor (EGFR), thereby inducing the progression of bone metastasis of cancer cells." (PMID 36497209, 2022). "Due to the overexpression of EGFR in the tumor, the anti-EGFR affibody-decorated nanogel showed high cellular uptake and PDT efficacy in EGFR-overexpressing cells." (PMID 35213974, 2022). "We next tested an in vitro model of tumor selectivity wherein both EGFR-overexpressing tumor cells and healthy donor derived HDFs were both present in triple co-culture." (PMID 35935988, 2022). "There are also studies about the CAR-T cells against CD133, as well as epidermal growth factor receptor (EGFR), with also favorable anti-tumor effect." (PMID 35629333, 2022). "Base PBPK model predictions for cetuximab tumor pharmacokinetics are separated by tumor model as cell-line specific values of EGFR expression were incorporated into the model predictions." (PMID 35054865, 2022). "Exact primary tumor location affects anti-EGFR antibody efficacy in a rather continuous than a dichotomous fashion in RAS/BRAF wild-type mCRC patients." (PMID 35158793, 2022). "EGFR-TKIs and PD-1/PD-L1 inhibitors can inhibit tumor growth through a variety of signaling pathways, but evidence of their effect on metabolic pathways is limited." (PMID 36034789, 2022). "The inhibition of TRAF6, while decreasing EGFR and other signaling pathway, halts tumor cell growth and therefore has a huge therapeutic potential." (PMID 35956111, 2022).
tumor (continued). "The novel anti-EGFR mAb, 806 (mAb806) targets a tumor-selective epitope of EGFR that is exposed on overexpressed, mutant, or ligand-activated forms of EGFR." (PMID 35326605, 2022). "Despite widespread use of an anti-EGFR monoclonal antibody to prepare tumor-targeted NPs, its large molecular weight and size, limits the penetration of this monoclonal antibody into the tumor microenvironment." (PMID 35281900, 2022). "Among patients with at least one EGFR-mutant tumor, approximately 72% of patients (52/72) had different EGFR mutations in individual tumors." (PMID 35740676, 2022). "With the assistance of antibodies, the viral fibre can bind to certain receptors (such as epidermal growth factor receptor, EGFR) highly expressed on the surface of tumour cells, resulting in selective infection." (PMID 36552019, 2022). "Recently, an anti-human EGF receptor (-EGFR)-Rap fusion protein has shown specific anticancer activity for EGFR positive tumor cells." (PMID 35322728, 2022). "The therapeutic effect of EGFR targeted treatment depends highly on the EGFR expression of the tumor." (PMID 35903247, 2022). "Our findings provide insight by revealing a previously unappreciated role for co-occurring RBM10 deficiency in limiting the initial response to EGFR inhibitor treatment in human EGFR-mutant LA by suppressing tumor cell apoptosis." (PMID 35579943, 2022). "In recent years, ceRNAs have been found to be involved in tumor development, and ceRNA networks play an important role in resistance to anti-EGFR mAbs in CRC." (PMID 36131281, 2022). "Tumor size, the extent of gastrectomy, postoperative complication, and EGFR expression level were significantly different between GC in the lesser curvature and GC in the greater curvature." (PMID 35984169, 2022). "In our previous study, 117 NSCLC tumor tissues were investigated to compare the results of the EGFR-LAMP and Therascreen assays." (PMID 35744511, 2022). "Tumor cells can reversibly regulate mutant EGFR expression, conferring distinct cellular phenotypes to adapt to environmental change." (PMID 36184613, 2022). "On day 6, EGFR CAR T cell treated animals displayed a clear influx of CBR2opt expressing CAR T cells into the tumor at the right flank of the mouse." (PMID 35836798, 2022). "Corresponding areas from the same tumor showed similar profiles for EGFR aptamer and antibody staining using fluorescence and light microscopy of the tumoral core and invasive border." (PMID 36297416, 2022). "We found that PD-L1 blockade impaired the efficacy of osimertinib in EGFR-mutant NSCLC cells despite the presence of the tumor microenvironment." (PMID 38089081, 2022). "In CAR-T cells, GITR co-stimulation yielded a comparable or even more robust anti-tumor activity than CD28 or 4-1BB G2 EGFR-targeted CAR-T cells in various tumor cell lines, including SKOV-3, A1847, and BxPC3." (PMID 35053463, 2022). "It has been proved that MNPs targeting EGFR under the action of AMF can selectively induce LMP in tumor cells that overexpress EGFR, and finally kill tumor cells." (PMID 36359744, 2022). "This degradation process of RTKs, including EGFR can be a new therapeutic target against EGFR-mediated tumor cells." (PMID 36438839, 2022). "Our results demonstrated that CB1 activation suppressed M2 macrophage differentiation and tumor growth by downregulating EGFR." (PMID 35641479, 2022). "The expression of p-Src and HIF-1α in persistent tumor cells increased and was dependent on EGFR-TKI treatment." (PMID 36612121, 2022). "Despite high tumor cell content in all samples, the level of EGFR amplification and expression was heterogenous among samples from the same patient." (PMID 36130485, 2022). "Our recent work uncovered tumor suppressor pathways that affect EGFR-driven lung tumor growth and sensitivity to tyrosine kinase inhibitors and reflect the mutational landscape and treatment outcomes in the human disease." (PMID 35252550, 2022).